ALB (albumin)
Diseases named in the same sentence as ALB in open-access papers (continued):
Sharing a sentence is not in itself a finding about the gene and the disease.
colorectal cancer (continued). "The aim of this retrospective study was to evaluate the significance of the C-reactive protein to albumin (CRP/ALB) ratio in colorectal cancer patients who received palliative chemotherapy." (PMID 27812440, 2016). "Preoperative albumin level is an objective, simple, and qualified nutritional assessment method for the evaluation of surgical risks in colorectal cancer patients." (PMID 26345703, 2015). "WDR81 has been found to be mutated in >10 % of the colorectal cancer cell lines and SERPINF2-WDR81 loci was reported to be one of the six significant loci for serum albumin as a result of transethnic meta-analysis." (PMID 27390838, 2015). "A study investigated the prognostic value of serum albumin in colorectal cancer patients and found serum albumin, age, tumor stage (Dukes' stage) and tumor differentiation to be independent prognostic factors for survival." (PMID 21176210, 2010). "It is well recognised that albumin concentration is a stage independent prognostic factor in patients with advanced colorectal cancer." (PMID 15213726, 2004). "While previous studies highlighted CA’s ability to induce apoptosis in breast and colorectal cancer via albumin nanoparticles, and trigger apoptosis while inhibiting Akt/mTOR signaling in GC, the precise mechanisms underlying its impact on GC chemosensitivity were unclear." (PMID 40696490, 2025). "Our research indicated that, while low albumin levels alone did not significantly predict bone metastases in colorectal cancer, the UAR was significantly associated with such metastases, as revealed by further ROC analysis." (PMID 41195265, 2025). "Materials and Methods: This retrospective study included 540 patients who were followed up after a diagnosis of early-stage colorectal cancer and whose albumin (ALB), alkaline phosphatase (ALP), neutrophil, platelet, and lymphocyte values were measured before treatment." (PMID 39941572, 2025). "The Systemic Immune-Inflammation Index (SII), calculated from platelet, neutrophil, and lymphocyte counts, reflects platelet-mediated inflammatory pathways and has been extensively applied in colorectal cancer prognosis, yet lacks nutritional parameters such as albumin." (PMID 41211422, 2025). "Another study revealed that preoperative albumin levels may be the best predictor of mortality after colorectal cancer surgery." (PMID 36874458, 2023). "Whether serum lactate dehydrogenase-to-albumin ratio (LAR) influenced the outcomes of colorectal cancer (CRC) patients after radical surgery remained unclear." (PMID 37770882, 2023). "A recent propensity-matched study found that glutamine supplementation mitigated the decline in albumin, total protein, and prealbumin levels and reduced ICs in patients who had undergone colorectal cancer surgery, with the difference being statistically significant." (PMID 37566134, 2023). "This study showed that a preoperative SpO2 < 96%, the Miles procedure or left hemicolectomy, perioperative surgical events, postoperative albumin infusion, distant tumor metastasis, and postoperative early ambulation were associated with PPLOS after laparoscopic colorectal cancer resection." (PMID 36566186, 2022). "The association between perioperative albumin levels and AL has not been fully investigated in patients with Colorectal cancers." (PMID 36105895, 2022). "The baseline data of 292 patients were retrospectively collected in this study and multivariate analysis showed that tumor location, preoperative albumin, preoperative lymphocyte, preoperative NLR, and SMA calcium volumes score were the risk factors for AL after colorectal cancer surgery." (PMID 36684195, 2022). "While albumin synthesis increased after colorectal cancer surgery with the administration of perioperative hypocaloric nutrition including isonitrogenous amounts of amino acids, parenteral amino acid intake did not increase albumin synthesis in septic patients." (PMID 34920728, 2021).
colorectal cancer (continued). "Serum albumin is positively correlated with the prognosis of colorectal cancer." (PMID 34355011, 2021). "Furthermore, the effect of PIC-loaded albumin NPs on the invasion activity of colorectal cancer cell lines (CaCo-2 and HT-29 cells) was assessed by using invasion assay." (PMID 31906321, 2020). "Therefore, SLA, LDH, and albumin can be used as a marker of metastasis in patients with colorectal cancer." (PMID 30627541, 2018). "Furthermore, the modified Glasgow Prognostic Score (mGPS), which comprises the serum C-reactive protein (CRP) and serum albumin levels, has been demonstrated as a favourable prognostic index for colorectal cancer (CRC) patients." (PMID 30419863, 2018). "ALB expression change in colorectal cancers is reported in many documents." (PMID 29511483, 2017). "According to recent research by Fujii, serum albumin is also superior to prealbumin for predicting short-term recurrence in patients with operable colorectal cancer, which is an interesting theme needed to be investigated in our FTMDT trial after long-time follow-up." (PMID 25649903, 2015). "The GPS has later been adapted to the currently more widely used mGPS, based on the finding that an abnormal albumin level alone and cancer-specific survival was similar to that of a normal albumin in patients undergoing potentially curable resection for colorectal cancer." (PMID 25861154, 2015). "However, correction with albumin or adjustment for gender, SES, albumin and CCI revealed a positive link between serum calcium and colon as well as colorectal cancer risk, particularly in women." (PMID 23866097, 2013). "For calcium based on age-specific cut-offs, a statistically significant association was only observed with colorectal cancer risk after adjustment with gender, SES, albumin, and CCI [HR: 1.27 (95% CI: 1.03-1.58) for those with high age-specific calcium levels compared to normal]." (PMID 23866097, 2013). "When examined in a cohort of patients undergoing potentially curable resection for colorectal cancer the results showed that the relationship between an abnormal albumin alone and cancer-specific survival was similar to that of a normal albumin." (PMID 21266974, 2011). "A study conducted in patients with colorectal cancer undergoing surgical treatment identified low serum albumin level, advanced Union for International Cancer Control (UICC) stage, and high carcinoembryonic antigen (CEA) level to be independent prognostic factors of cancer-specific survival." (PMID 21176210, 2010). "Therefore, the results of the present study are consistent with the concept that the systemic inflammatory response is a major determinant of albumin concentrations in patients with advanced colorectal cancer." (PMID 15213726, 2004). "Indeed, the reduction in circulating albumin concentrations, as well as an increase in C-reactive protein, are linked with poor outcomes in patients with colorectal cancer independent of tumor stage and host factors." (PMID 32708140, 2020). "In contrast, the use of HA as a targeting ligand in the albumin nanoparticles, PP-HA-BSA-NPs, significantly improved drug delivery in CD44-expressing triple-negative breast cancer and colorectal cancer cells." (PMID 41002533, 2025). "The results revealed that the independent risk factors for the development of recent complications after colorectal cancer surgery were PNI, albumin levels, ASA, and tumor diameter." (PMID 39568563, 2024). "Combining handgrip strength, serum albumin level, and TNM stage would help improve the predictive effect of GLIM criteria for colorectal cancer patients post-radical surgery and benefit the individual prognostic prediction of colorectal cancer." (PMID 39502874, 2024). "The SIS, which incorporates serum albumin and LMR to reflect systemic inflammation and nutritional status, was first introduced as a prognostic tool in colorectal cancer and clear cell renal carcinoma." (PMID 39767217, 2024).
colorectal cancer (continued). "In summary, the findings of this study highlight that PNI, Albumin, ASA, and Tumor diameter serve as independent predictors of recent postoperative complications in colorectal cancer patients." (PMID 39568563, 2024). "CA-loaded polymeric nanoparticles, specifically bovine serum albumin (BSA) nanoparticles, enhance CA’s antitumor activity against colorectal cancer cells." (PMID 38202397, 2023). "Circulating fibrinogen to pre-albumin ratio (FPR) and albumin to fibrinogen ratio (AFR) are effective factors for predicting the prognosis of colorectal cancer (CRC)." (PMID 35346200, 2022). "The relationships between the neutrophil-albumin ratio (NAR) and clinicopathological factors of colorectal cancer (CRC) patients." (PMID 36458178, 2022). "CCM-modified-ICG and Abraxane (bovine serum albumin (BSA)-coated paclitaxel (PTX) formulation) were loaded on the LDH NSs to form LIPC NSs (LDH-ICG/PTX-CCM NSs) for the targeted photochemotherapy of colorectal carcinoma (CRC)." (PMID 36233164, 2022). "Gennaro Galizia’s study established a new prognostic tool, the Naples prognostic score, including albumin, cholesterol, NLR, and LMR, which showed a better performance than the existing single index in predicting the prognosis of colorectal cancer patients." (PMID 34195071, 2021). "This study aimed to investigate the prognostic value of the combination of preoperative lymphocytes, albumin, and neutrophils (LANR) in patients with resectable colorectal cancer." (PMID 34150609, 2021). "In this study, we have explored the potential of the human albumin-derived peptide, EPI-X4, as a suitable ligand to target colorectal cancer via the cell surface protein CXCR4, a chemokine receptor overexpressed in cancer stem cells." (PMID 34208189, 2021). "In colorectal cancer patients, white blood cell count, platelet, ApoA, FFA, IL-6 and TNF-α increase significantly, while albumin, prealbumin and ApoE decreased significantly." (PMID 31788012, 2019). "After taking albumin into account, a positive association was observed between serum calcium and risk of oesophageal and colon cancer in women, as opposed to the suggested inverse relation between dietary calcium and colorectal cancer, and a lack of association with oesophageal cancer." (PMID 23866097, 2013). "Another study in 337 patients with colorectal cancer liver metastases found Dukes stage, number of metastases, and serum concentrations of CEA, ALP, and albumin to be independent predictors of survival." (PMID 21176210, 2010). "A study in colorectal carcinoma patients found that a preoperative CEA level greater than or equal to 5 ng/mL and albumin level less than 3.5 g/dL predict a poor survival chance for colorectal carcinoma patients." (PMID 21176210, 2010). "Recently, the combination of C-reactive protein and albumin, known as the Glasgow Prognostic Score (GPS) has been evaluated pre-operatively in patients undergoing potentially curative surgery for colorectal cancer." (PMID 17923866, 2007). "In survival studies involving patients with colorectal cancer who received both surgical and non-surgical treatments, albumin has been utilized either as a component of the study or as part of a prognostic score." (PMID 41195265, 2025). "Recently, a study proposed a combined value of muscle density and albumin level in patients with non-metastatic colorectal cancers." (PMID 39614916, 2024). "Systemic inflammatory factors, such as lymphocytes, monocytes and neutrophils, and blood biochemical indicators related to nutritional status, such as C-reactive protein levels (CRP) and albumin levels (ALB), are valuable prognostic indicators for cancers including colorectal cancer." (PMID 34150609, 2021).
colorectal cancer (continued). "Most promising and meaningful modifications were observed on the surface of vitamin D-binding protein (VDBP), complement C4-A (CO4A), X-ray repair cross-complementing protein 6 (XRCC6), Plasma protease C1 inhibitor (IC1), and albumin (ALBU), which are related to colorectal cancer developing." (PMID 32660089, 2020). "The Glasgow Prognostic Score (GPS), which predicts outcome following surgery for colorectal cancer, also considers serum albumin level as an inflammatory marker rather than an indicator of nutrition." (PMID 23590192, 2013). "Following fruquintinib treatment, patients with colorectal cancer and high PNI levels demonstrated elevated levels of white blood cells, lymphocytes, basophils, red blood cells, hemoglobin, platelets, total protein, and albumin, indicative of a pronounced therapeutic effect and extended OS time." (PMID 39624124, 2024). "In addition, a total of five types of predominant cancers (NSCLC, melanoma, hepatobiliary cancer, colorectal cancer, and head and neck cancer) were collected in this study and we observed that the SII/ALB ratio demonstrated prognostic relevance across these cancers." (PMID 38935663, 2024). "The Inflammation-Immunity-Nutrition Score (IINS), originally developed as a prognostic score for patients with colorectal cancer, was constructed based on the sum of classification scores of preoperative high-sensitivity C-reactive protein (hsCRP), lymphocyte (LYM), and albumin (ALB)." (PMID 39061188, 2024). "They identified five key factors (neutrophils, lymphocytes, platelets, albumin, and CRP) reflecting systemic inflammation derived from NLR, PLR and CAR, and examined the best combination with highest accuracy to predict oncological outcomes in colorectal cancer patients." (PMID 33507925, 2021). "In addition, the prognostic nutritional index (PNI, based on serum albumin and lymphocyte counts) and the serum C-reactive protein (CRP)/serum albumin ratio (CAR) were shown to be effective predictors of postoperative complications after colorectal cancer surgery." (PMID 33879101, 2021). "This study suggests that pretreatment albumin, MIP-1β, non-liver metastatic disease and Treg infiltration may be potential predictive biomarkers of regorafenib/nivolumab in pMMR colorectal cancer." (PMID 38339307, 2024). "Pretreatment albumin, MIP-1β, non-liver metastatic disease and regulatory T-cell infiltration may be potential predictive biomarkers of regorafenib/nivolumab in pMMR colorectal cancer." (PMID 38339307, 2024). "However, the prognostic significance of the combination of lymphocyte, albumin, and neutrophil (LANR) in colorectal cancer has not been well-investigated to date." (PMID 34150609, 2021). "Our study suggests high pretreatment albumin levels, low pretreatment MIP-1β levels, non-liver metastasis, low Treg density and different gene expression in the tumor microenvironment may be potential predictive biomarkers of nivolumab plus regorafenib in refractory pMMR colorectal cancer." (PMID 38339307, 2024).
congestive heart failure (184 papers, 2005 to 2026). Failure of the heart to pump a sufficient amount of blood to meet the needs of the body tissues, resulting in tissue congestion and edema. "Background and Objectives: In this study, we aimed to investigate the prognostic value of the C-reactive protein to albumin ratio (CAR) for all-cause mortality in patients with chronic heart failure with reduced ejection fraction (HFrEF)." (PMID 38541167, 2024). "The risk factors associated with 30-day mortality include age, congestive heart failure, cerebrovascular disease, malignant cancer, white blood cell count, bilirubin levels, albumin levels, glucose levels, VTC, GCS score, and SOFA score." (PMID 38509460, 2024). "Several diseases and abnormalities including chronic heart failure and PH, were associated with low levels of albumin as a result of hemodilution caused by volume overload." (PMID 37781288, 2023). "Greater deciles of age over 50 years, diagnoses of chronic obstructive pulmonary disorder or chronic heart failure, and laboratory abnormalities in alkaline phosphatase, hematocrit, and albumin contributed highest risk score weights for mortality." (PMID 37867787, 2023). "Our study revealed linear association between serum albumin and all-cause mortality on 14th, 28th, and 90th days in patients with congestive heart failure respectively." (PMID 36171266, 2022). "The results showed that serum albumin is an independent risk factor for 14th, 28th and 90th day all-cause mortality, and has a linear relationship with all-cause mortality in congestive heart failure." (PMID 36171266, 2022). "Those patients who died in-hospital were significantly older, more had respiratory failure, loss of consciousness, chronic heart failure, malignancies, lower BMI, hemoglobin levels, albumin levels, and Barthel Index on admission." (PMID 33619334, 2021). "Reduced albumin levels are usually caused by starvation, liver insufficiency, kidney disease, congestive heart failure, or parasitic disease." (PMID 34083932, 2021). "Previous studies have identified many risk factors for early dialysis mortality, such as old age, chronic heart failure, catheter use, low albumin, low hemoglobin, and high estimated glomerular filtration rate at dialysis initiation." (PMID 33118948, 2020). "Drawing of serum albumin in the post-hospitalization period was associated with 1.6-fold higher risk, whereas documentation of congestive heart failure in the EMR was associated with 65% lower risk, of other vs. no readmissions." (PMID 30064380, 2018). "A recent study from 1161 diabetic patients on hemodialysis revealed association of carbamylated albumin with congestion heart failure and sudden cardiac death." (PMID 27973558, 2016). "In diabetic patients on hemodialysis, serum carbamylated albumin was strongly associated with cardiac damage, risk of congestive heart failure, and sudden cardiac death." (PMID 27973558, 2016). "In the Dialysis Outcomes and Practice Patterns Study (DOPPS), older age, catheter vascular access, albumin concentration <3.5 g/dL, phosphorus concentration <3.5 mg/dL, cancer, and congestive heart failure were all associated with 1-year mortality." (PMID 24058552, 2013). "Besides that, the presence of congestive heart failure, dementia and low albumin levels are associated with 30 days mortality in such kind of patients." (PMID 33510882, 2020). "Multivariate LR analysis showed that congestive heart failure (OR, 0.015, 95%CI, 0.001-0.211; P = 0.002), dementia (OR, 0.029, 95%CI, 0.002-0.516; P = 0.016), and albumin (OR, 0.049, 95%CI, 0.006-0.383; P = 0.049 ) were associated with 30 days mortality in intermediate-high risk acute PE patients." (PMID 33510882, 2020). "They founded that male gender, age over 85 years, congestive heart failure, severe peripheral vascular disease, dysrhythmia, severe behavioral disorders, active malignancy, serum albumin, and impaired mobility were independently associated with 3-month mortality." (PMID 29317867, 2017).